CCR7 (C-C motif chemokine receptor 7)
Diseases named in the same sentence as CCR7 in open-access papers (continued):
Sharing a sentence is not in itself a finding about the gene and the disease.
tumor (continued). "In addition to immune cells, the CCR7/CCL19 axis is expressed in airway smooth muscle cells, myofibroblasts, and fibroblasts (Rodríguez-Fernández and Criado-García, 2020), and is involved in biological processes such as tissue repair, endothelial-mesenchymal transition, and tumor metastasis." (PMID 36589450, 2022). "In addition, our study revealed that MXRA8 expression correlated with the expression of multiple metastasis-associated chemokines (CXCL12, CXCL13, CCL9, CCL21, CXCR4, CXCR5, and CCR7), suggesting that MXRA8 may be involved in tumor invasion and metastasis by regulating the secretion of chemokines." (PMID 36703779, 2022). "In addition, the oxysterol secreted by tumor cells has been shown to impair the antigen presentation of dendritic cells (DC) by LXR-α signaling activation, thus mediating downregulation of the expression of C-C chemokine receptor type 7 (CCR7), a lymphoid homing marker of DC, on the DC cell surface." (PMID 34820325, 2021). "Notably, single-dose anti-CCR7 treatment seemed to delay disease onset to week 8 (as determined by the first appearance of bioluminescent signals) and also tended to modestly reduce tumor burden, although no statistical differences were found between groups." (PMID 33110606, 2020). "Moreover, Mo-DCs, unlike both cDC subsets, failed to upregulate CCR7 in tumours." (PMID 28008905, 2016). "Using OX40LHu-CD4 (Tnfsf4)-reporter mice, we confirmed that some tumour CCR7+ DCs express OX40L, but it was not expressed by tumour cDCs or CCR7+ DCs in the dLN." (PMID 38267413, 2024). "Tumour infiltrated T cells expressed TRAC, IL7R, CD8A, and were negative for naïve T cell marker CCR7." (PMID 38267611, 2024). "In the absence of CCR7, antitumor T cells in the DLN are no longer efficiently stimulated despite loading of DCs with tumor antigens." (PMID 37183207, 2023). "Since CD83+ T cells included both CCR7+ and CCR7− cells, and CD83− cells were mostly negative for CCR7 as was seen in the tumor model, we isolated three populations (CD83+CCR7+, CD83−CCR7+, and CD83− cells) and restimulated them in vitro." (PMID 36906640, 2023). "The six critical genes, including CCR7, FCGR2B, BTLA, CD6, CD3D and CD3E, play important roles in favoring tumor progression and promoting negative immune-regulatory effects." (PMID 36291815, 2022). "By contrast, cell surface levels of other chemokine receptors, including CXCR5, CCR7 and CCR5, were not altered in vitro, or moderately increased in vivo after infiltrating tumours (Fig EV3C)." (PMID 31803974, 2020). "The majority of tumor-infiltrating mast cells expressed CXCR4 but not CCR2, CCR4, CCR5, CCR7, CXCR1, CXCR2 or CXCR7, while, mast cells in peritumoral or non-tumor tissues showed lower CXCR4 expression." (PMID 30808413, 2019). "Whereas naïve T cells (CD45RA+/CCR7+) constituted 33.2 ± 18.3% of T cells in the peripheral blood of healthy controls, their percentage in PBMC HNSCC was 22.4 ± 14.6%, in tumor samples 4.1 ± 3.8% and in non-cancerous mucosa 7.7 ± 7.2% (left plot)." (PMID 28574843, 2017). "In the tumor samples, EWS cells were negative for CCL21 and CCR7, while infiltrating immune cells did show expression of both CCL21 and CCR7." (PMID 27369431, 2016). "The combination of sialidase treatment with tumor-antigen upload did not alter the expression of other co-stimulatory molecules, such as CD40, and of the chemokine receptor CCR7, when compared with fully sialylated MoDCs (results not shown)." (PMID 27203391, 2016). "The expression levels of CCR7, CXCR4 and VEGF-C did not correlate with the clinicopathological parameters, including those of age, gender, tumor size and histological grade (P>0.05)." (PMID 23761820, 2013). "In this series CCR7 was found to be expressed only on stromal cells either with myofibroblastic morphology and α-SMA expression or with dendritic morphology, but not on tumor cells." (PMID 21624121, 2011).
tumor (continued). "However, in LLC lung tumor-bearing Ccr7-/- mice with VEGFR blockade, M057 treatment no longer inhibited tumor growth." (PMID 38250037, 2024). "Moreover, CCL21-Ser expression was undetectable in tumor tissues, suggesting the contribution of host-derived CCL21-Ser and CCR7 on nontumor cells to B16–F10 tumor growth." (PMID 37664721, 2023). "Similarly, CCR7-negative TEFF and TEM rather than CCR7-expressing naïve or TCM are necessary to effective anti-tumor responses." (PMID 33841445, 2021). "Given that CCR7 did not influence survival in ACC, it is probably not involved in tumor progression, but it could play a role in adrenocortical homeostasis." (PMID 34830848, 2021). "Given the knowledge that in vitro expanded Vγ9Vδ2 T cells –do not present antigen in the absence of added tumor antigen –, the most rational setup for maximal cytotoxic effector function in ACT would be to use Vγ9Vδ2 T cells that do not express CCR7, e.g. have been expanded for 14 days or more." (PMID 34149689, 2021). "Interestingly, CDR45RA + CCR7− effector CD4+ cells, which represent T central memory cells, were significantly less expressed in PD-L1 positive tumours compared to PD-L1 negative tumours (p = 0.01)." (PMID 34206956, 2021). "In silico criteria for tumor selection may include the presence of GM-CSF, IL-3 and FLT3-L, ligand expression of chemokine receptors CXCR4, CCR7, and CXCR3 and the absence of very high GM-CSF level." (PMID 33013879, 2020). "CD1a+ DCs within the tumour area and normal kidney tissue demonstrated co-expression for CCR6, whereas no expression for CCR7 could be observed as determined by immunohistochemistry and double-immunofluorescence studies." (PMID 20969772, 2010). "Further, there was a significant correlation between CCR7 expression and lymph node metastasis (p < 0.001); CCL21 was especially highly expressed in lymph nodes metastasis tumor cells (68%), which was not the case in primary tumor cells (P = 0.004)." (PMID 20181250, 2010). "However, since CCR7 and the TGF-β1 receptor are not restricted to DCs, other immune cells may also contribute to these effects on tumor growth and metastasis." (PMID 31191539, 2019).
cancer (271 papers, 2010 to 2026). A tumor composed of atypical neoplastic, often pleomorphic cells that invade other tissues. "Dysregulated expression of CCL19 and its receptor CCR7 has been widely implicated in various cancers." (PMID 40895068, 2025). "Further research is needed to fully understand the molecular mechanisms underlying CCR7 function in cancer and to determine its potential as a therapeutic target." (PMID 40299690, 2025). "We asked if the time, tissue, and treatment-associated heterogeneity in CCR7+ DCs observed in our murine model was pertinent to human cancers." (PMID 38267413, 2024). "CCR7 (C-C chemokine receptor type 7) signaling, which mediates the migration of both cancer and immune cells to the lymph nodes, is implicated in lymph node metastases and several chronic inflammatory diseases." (PMID 37974170, 2023). "CCR7 was linked to local recurrence, being male and smoking, which were risk factors for poor prognosis, suggesting a role for CCR7 in cancer progression." (PMID 35203305, 2022). "Crucially, the elevated CCR7 expression level caused by a deficiency in let-7a expression level is intricately linked to the metastasis and progression of cancer." (PMID 36243683, 2022). "In lymphoid malignancies, the role of CCR7 in hallmark deregulations of cancer such as enhanced migration or death resistance, can be associated to functional differences between CCR7-expressing normal and malignant cells." (PMID 34778050, 2021). "CCR7 is also implicated in different cancers, where chemotactic trafficking allows cancer cells to spread." (PMID 34770763, 2021). "Concordant to our data, recently it has been pointed out that CCL21/CCR7 is linked with cancer recurrence, smoking, and poor prognosis in HN cancer." (PMID 32961854, 2020). "The same mechanism causes the retention of cancer cells with CCR7 expression in a lymph node and the formation of metastasis to this peripheral lymphoid organ." (PMID 32781743, 2020). "Metastasis is extremely inefficient and depends on many factors, particularly on the expression of chemokine receptors on cancer cells, including CCR7 associated with lymph node metastasis." (PMID 32781743, 2020). "Small molecule ligands designed to silence CCR7 thus have great potential to address lymph node metastasis, a major cause for cancer-associated mortality." (PMID 31442409, 2019). "Although CCR7 and clinical associations have been revealed in a large variety of malignant tumors, only a few are currently known for esophageal cancer." (PMID 24766770, 2014). "Recent studies also suggest that let-7 regulates metastasis-associated genes such as MYH9 and C-C chemokine receptor type 7 (CCR7) to facilitate invasion ability of cancer cells." (PMID 23075324, 2012). "In addition to its role in immune-cell migration, CCR7 has also been implicated in various pathological conditions, including cancer." (PMID 40299690, 2025). "Results of our study suggest that a loss of CCR6 expression and an increase in CCR7 expression may allow cancer cells to migrate to lymph nodes and lead to development of metastasis." (PMID 37316552, 2023). "This cancer uniquely possessed truncated CCR7, which appeared to be gain-of-function mutations." (PMID 35203305, 2022). "Although CCR7 is associated with a variety of human diseases, such as immunological disorders, inflammatory diseases, and cancer, this target is underexplored in drug discovery and there are no potent and selective CCR7 small molecule antagonists available today." (PMID 35370691, 2022). "In previous studies, CCR7/CCL19 was reported to be associated with some types of cancer." (PMID 34544443, 2021). "Together, CCR7 signaling system has been implicated in diverse biological processes such as lymph node homeostasis, T cell activation, immune tolerance, inflammatory response and cancer metastasis." (PMID 26504105, 2015).
cancer (continued). "Therefore, a possible role of CCR7 in cancer development and metastasis is its association with cancers, as well as being linked to the expression of its ligands, CCL19 and CCL21." (PMID 22251626, 2012). "Indeed, CCR7 is implicated in cancer; however, whether targeting CCR7 using agonists or antagonists for the intervention in cancer remains debatable." (PMID 34361107, 2021). "Ki67 and cleaved-caspase 3 immunohistochemical staining indicated increased apoptosis and decreased proliferation of cancer cells following cisplatin treatment upon blockade of the CXCL14/CCR7/STAT3/ERCC4 axis." (PMID 40898244, 2025). "mregDCs have been identified in normal tissues, infections, autoimmune conditions, and various cancers, are also termed migratory DCs, CCR7+ DCs, or LAMP3+ DCs in some studies." (PMID 41430039, 2025). "C7Mab-7, developed by the CBIS method, accelerates the development of CCR7-targeted antibody therapies and cancer diagnostics." (PMID 40028039, 2025). "CellChat analysis revealed that the exhaustion phenotype of CD4+ (Treg, CH25H+, and CCR7+ naive) and active CD8+ (TEM and MAIT) cells was associated with significant intercellular communication with the cancer‐pre cells we identified." (PMID 40860436, 2025). "CCR7 is therefore considered a potential therapeutic target for the development of new cancer treatments." (PMID 40299690, 2025). "Spatial, single-cell, and intravital analyses of human cancers and mouse models reveal that CCR7+ DCs form perivascular clusters." (PMID 41421339, 2025). "Inspired by these findings, and considering the significant role of bioinformatics in cancer research, our study leverages biological information to identify CCR7 as a potential key gene in the action of lenalidomide in DLBCL." (PMID 39735670, 2025). "Its expression is a pre-requisite in DC immunotherapy because high levels of CCR7 expression directly translate to survival benefits in cancer patients." (PMID 40005712, 2025). "Separately, many cancer cells express CCR7, linking the lymph node homing effects with cancer cell metastasis to lymphoid tissue." (PMID 38786066, 2024). "Despite these advances, the role of CCR7/ACKR4 signaling is largely cancer-type dependent, showing either an unfavorable or beneficial role." (PMID 39456552, 2024). "High expression of CCR7, IL2RG, CXCL9 and MAPK10 was associated with elevated drug sensitivity of cancer cells, while high expression of FLT3 was associated with diminished drug sensitivity of cancer cells to one drug (INK-128)." (PMID 38438469, 2024). "Provision of IL-15 within the TME likely involves CCR7+ DCs, which express high levels of IL-15 and IL-15RA, co-localize with NK cells in human cancers and can support further molecular interactions such as PVR:TIGIT55,71,72." (PMID 38267402, 2024). "Tumor necrosis factor -α, a proinflammatory cytokine, can increase CCR7 expression in cancer cells, promoting the production of CCL21 in human lymphatic endothelial cells." (PMID 39114657, 2024). "Hypoxia and prostaglandin E2 increase the expression of CCR7 in cancer cells, thereby affecting cell stemness and proliferation potential." (PMID 38552222, 2024). "As a result, CCL19/CCR7 is crucial for the immune system’s control of inflammatory bowel disorders, infection prevention, and cancer suppression." (PMID 38882664, 2024). "Four key genes CCL2, CCR7, LY96, and PTPRC, from ClusterK1 and five genes AURKA, CDK1, CCNA2, FEN1, and PLK1 from ClusterK2, were associated with at least one type of cancer." (PMID 38872418, 2024). "The results first demonstrated the role of CCR7 in immune mouse cancer in vivo, but the authors just focused on cancer stem like-cells and did not explore the TME alterations." (PMID 38539232, 2024). "Tem cells are usually characterized by a CD45RO+C-C motif chemokine receptor 7 (CCR7)-killer cell lectin-like receptor G1 (KLRG1)high phenotype in patients with cancer." (PMID 38576625, 2024).
cancer (continued). "In esophageal squamous carcinoma, activation of CCR7 increases VEGF-A expression in cancer cells by increasing angiogenesis through activation of NF-κB." (PMID 37963845, 2023). "Hypoxia and prostaglandin (PGE2) increase CCR7 expression in cancer cells, leading to the elevation of VEGF-C and VEGF-D expression, which in turn, leads to lymphangiogenesis." (PMID 37600570, 2023). "CCR7, coupled with its natural ligands CCL19 and CCL21 (the CCL19/21-CCR7 axis), controls the trafficking of DCs and metastasis and invasion of some malignant tumor cells." (PMID 37198402, 2023). "For example, LECs promote the invasion of lymphatic vessels by inducing the migration of cancer cells expressing CCR7 to pre-metastatic niches, and the expression of CCR7 is associated with lymphatic vascular invasion and lower survival rate." (PMID 37803421, 2023). "In the sample of patient B19, four cancer related genes CCR7, AKT1, SLIT2 and CDK6 were found with HPV integrations before treatment, and none was found after treatment." (PMID 37914994, 2023). "CCL21 produced by lymphatic endothelial cells generates a concentration gradient that induces migration of cancer cells to the lymph nodes (LNs) in a CCR7-dependent manner." (PMID 37664721, 2023). "We further identified a DC subset with elevated expression of LAMP3, FSCN1, and CCR7 as migratory DCs (migDCs), as described recently in healthy thymus and various cancer types including breast." (PMID 36609566, 2023). "To uncover potential distinctions between HDs and patients with various cancer types, we examined the distribution frequencies of the four subsets within memory T cells, excluding the naïve CCR7+CD45RA+ phenotype." (PMID 37898752, 2023). "Chemokines (CCR1, CCR2, CCR3, CCR4, CCR5, CCR6, CCR7, and CCR8) and receptor genes (CXCL1-17, CCL1-14, CCL16-26) were positively associated with necroptosis levels in various cancers." (PMID 36170029, 2022). "As previously discussed, many cancers frequently metastasize to lymphoid tissue, for which CCR7 is often the perpetrator." (PMID 35203305, 2022). "The data indicated that in different cancers, CCR7 plays distinct roles in directing cells to lymph nodes, the skin or to the central nervous system." (PMID 35203305, 2022). "Cancer cells that express CCR7 behave in a similar fashion to immune cells, such that they also follow chemotactic gradients that lead to lymph node migration and metastasis." (PMID 35203305, 2022). "Regarding the histopathological type of cancer, a higher CCR7 and CCL19 mRNA expression level was observed in the AC group compared to the SCC group." (PMID 35160116, 2022). "Cancer tissue showed correlative responses of CCR7 and HIF-1α, along with a more malignant phenotype." (PMID 35203305, 2022). "In this section, expression of CCR7 during cancer initiation, progression, metastasis and at diagnosis is discussed." (PMID 35203305, 2022). "Based on the fact that CCR7 functions in the inflammatory/immune response, many strategies have been developed to exploit this axis for the treatment of cancer." (PMID 36510567, 2022). "In order to have a broad view of CCR7 expression pattern in pan-cancer scale, we downloaded RNAseq data of TCGA tumors from TIMER2.0 database." (PMID 35904690, 2022). "The high levels of homology of mouse and human receptors and ligands make mouse models useful for studying CCR7 function relevant to cancer in humans." (PMID 35203305, 2022). "CC chemokine ligand 21/chemokine receptor 7 (CCL21/CCR7) facilitates growth and metastases of a variety of cancers." (PMID 35860597, 2022). "Considering the importance of CCR7, in this review, we seek to address the importance of CCR7 in immune cell regulation, lymph node homing, immune tolerance, different types of cancer, and CCR7 as a therapeutic and prognostic marker." (PMID 35874608, 2022).